AGGF1 (angiogenic factor with G-patch and FHA domains 1)
Description:
Promotes angiogenesis and the proliferation of endothelial cells. Able to bind to endothelial cells and promote cell proliferation, suggesting that it may act in an autocrine fashion.
Synonyms: GPATC7; GPATCH7; VG5Q; HSU84971; FLJ10283; HUS84971
Tractability: Antibody: UniProt places it where antibodies can reach, with high confidence; its Gene Ontology location is reachable by antibodies, with high confidence. PROTAC: ubiquitination databases record sites on it.
Gene: Protein-coding gene on chromosome 5 (77,029,251 to 77,065,234, forward strand). Ensembl gene ENSG00000164252.
Subcellular location: Cytoplasm; Secreted
Pathways (Reactome):
Disease: Signaling by BRAF and RAF1 fusions
Gene Ontology:
Molecular function: identical protein binding; protein binding; nucleic acid binding
Biological process: cell adhesion; positive regulation of angiogenesis; positive regulation of endothelial cell proliferation; vasculogenesis
Cellular component: cytoplasm; extracellular region; perinuclear region of cytoplasm
Genetic constraint (gnomAD): Loss-of-function variants: 43 observed, 68.64 expected, observed/expected ratio (o/e) 0.63, 90% interval 0.49 to 0.81. The upper end of that interval is the gene's LOEUF score, 0.81, which puts it in group 3 of 6, group 1 being the genes least tolerant of losing a copy. Missense variants: 736 observed, 793.28 expected, observed/expected ratio (o/e) 0.93, 90% interval 0.87 to 0.99. Synonymous variants: 276 observed, 278.12 expected, observed/expected ratio (o/e) 0.99, 90% interval 0.9 to 1.1.
Homologues: Orthologues: chimpanzee AGGF1 (99% identical), pig AGGF1 (87% identical), guinea pig AGGF1 (82% identical), dog AGGF1 (78% identical), mouse Aggf1 (78% identical), rat Aggf1 (78% identical), rabbit AGGF1 (61% identical), tropical clawed frog aggf1 (51% identical), zebrafish aggf1 (45% identical), Drosophila melanogaster CG8079 (25% identical), Caenorhabditis elegans Y55D9A.2 (16% identical).
Diseases named in the same sentence as AGGF1 in open-access papers:
AGGF1 is named in the same sentence as 48 diseases in open-access papers, as found by Europe PMC text mining. Sharing a sentence is not in itself a finding about the gene and the disease. The quoted sentences say what the papers report.
glioblastoma (6 papers, 2019 to 2025). The most malignant astrocytic tumor (WHO grade IV). "AGGF1 is a common oncogene with high levels within tumors such as glioblastoma, colorectal, and gastric cancers." (PMID 41578779, 2025). "Knockdown of KLF5 also represses PI3K, AKT, and ERK1/2 activities, together with AGGF1, contributing to suppressed angiogenesis in glioblastoma." (PMID 33493334, 2021). "MCM3AP-AS1 induces angiogenesis in glioblastoma by regulating the miR-211/KLF5/AGGF1 axis." (PMID 34271873, 2021). "MCM3AP-AS1 is also upregulated in glioblastoma and regulates angiogenesis through the miR-211/KLF5/AGGF1 axis." (PMID 34256796, 2021). "In glioblastoma multiforme, MCM3AP-AS1 is also upregulated and interacts with the miR-211/KLF5/AGGF1 axis to promote tumor angiogenesis." (PMID 34271873, 2021). "In addition, KLF5 boosts glioblastoma angiogenesis via enhancing the promoter activity of angiogenic factor with G-patch and FHA domain 1 (AGGF1), which is identified as a pro-angiogenic factor and associated with angiogenesis in various cancers." (PMID 33493334, 2021).
gastric cancer (4 papers, 2017 to 2025). A primary or metastatic malignant neoplasm involving the stomach. "Numerous studies have reported the aberrant expression of AGGF1 in cancer tissues and its involvement in malignant progression, such as in gastric cancer, hepatocellular carcinoma, and serous ovarian cancer." (PMID 31881864, 2019). "Collectively, knockdown of AGGF1 inhibits the invasion and migration of gastric cancer via epithelial–mesenchymal transition through Wnt/β-catenin pathway." (PMID 30858758, 2019). "However, the mechanisms involved in the regulation of AGGF1 in gastric cancer (GC) still remain unclear." (PMID 30858758, 2019). "In vitro, we determined that AGGF1 promoted CRC cell wound healing, migration, and invasion, which indicates the potential involvement of AGGF1 in CRC metastasis and is consistent with the results of studies in gastric cancer and hepatocellular carcinoma." (PMID 31881864, 2019). "As previously reported in gastric cancer and HCC, the positive AGGF1 expression was positively related with aberrant expression of VEGF and higher MVD." (PMID 29340079, 2017). "In gastric cancer and HCC patients, expression of AGGF1 was significantly higher than that in adjacent noncancerous samples and increased AGGF1 serves as an unfavorable prognostic factor." (PMID 29340079, 2017).
coronary artery disease (3 papers, 2012 to 2020). "Treatment with the angiogenic factor AGGF1 dramatically improves survival and cardiac function in mouse models for coronary artery disease and myocardial infarction by activating autophagy and angiogenesis." (PMID 27513923, 2016). "This study establishes the angiogenic factor AGGF1 as a novel target and agent that can successfully treat coronary artery disease and acute myocardial infarction and dramatically improve survival and cardiac function in mouse models." (PMID 27513923, 2016). "AGGF1 is an angiogenic factor with therapeutic potential to treat coronary artery disease (CAD) and myocardial infarction (MI)." (PMID 27513923, 2016). "Moreover, AGGF-1, a potent therapeutic candidate for coronary artery disease, induces angiogenesis by promoting autophagy in endothelial cells." (PMID 32796816, 2020). "Therapeutic angiogenesis with AGGF1 may be beneficial to patients with not only PAD, but also other ischemic conditions such as ischemic heart disease, MIs, and strokes." (PMID 23110058, 2012).
hepatocellular carcinoma (3 papers, 2017 to 2024). A malignant tumor that arises from hepatocytes. "Our study was to investigate the impact of taurolactone, a novel anti-tumor and anti-angiogenic drug, on AGGF1, an angiogenic factor, and angiogenesis mimicry in patients diagnosed with hepatocellular carcinoma (HCC)." (PMID 38773427, 2024). "However, the function and the prognostic values of AGGF1 in hepatocellular carcinoma remain poorly understood." (PMID 29340079, 2017).
liver fibrosis (3 papers, 2016 to 2025). "Notably, Angiogenic factor with G patch and FHA domains 1 (AGGF1) regulates liver fibrosis and may contribute to Metabolic dysfunction-associated steatohepatitis (MASH) pathogenesis just like Vanin-1 (VNN1) and Suv39h2, two histone methyltransferases." (PMID 41272759, 2025). "5-Azacytidine, a DNMT inhibitor, restored Aggf1 expression, which led to improvement of liver fibrosis in a SMAD7-dependent mechanism." (PMID 31718044, 2019). "DNA methylation directly modulates liver fibrosis by targeting AGGF1." (PMID 41272759, 2025). "One of these genes is angiogenic factor with G patch and FHA domains 1 (Aggf1), which is downregulated in different models of liver fibrosis and in activated HSC through increased CpG methylation of DNA surrounding the Aggf1 promoter." (PMID 31718044, 2019).
myocardial infarction (3 papers, 2016 to 2020). Gross necrosis of the myocardium, as a result of interruption of the blood supply to the area, as in coronary thrombosis. "Notably, the expression of AGGF1 is induced in ischemic myocardium, and AGGF1 knockout mice show reduced autophagy and angiogenesis and larger damaged areas after myocardial infarction." (PMID 33363161, 2020). "In mice, inhibition of autophagy by bafilomycin, or genetic beclin heterozygosity as well as ATG5 knockout impairs angiogenesis post myocardial infarction, whereas the angiogenic factor AGGF1 enhances therapeutic angiogenesis through JNK-mediated stimulation of endothelial autophagy." (PMID 31580256, 2019).
cardiac hypertrophy (2 papers, 2016 to 2017). "In summary, we show that AGGF1 haploinsufficiency affects ER stress signaling and causes cardiac hypertrophy and heart failure." (PMID 28743963, 2017). "At 28 d after treatment, AGGF1 treatment inhibited early cardiac hypertrophy associated with MI." (PMID 27513923, 2016). "Pressure overload by TAC induced cardiac hypertrophy and heart failure, which was exacerbated significantly in Aggf1+/− mice." (PMID 28743963, 2017). "The association between downregulation of AGGF1 and increased ER stress signaling was also identified in a TAC model for cardiac hypertrophy and heart failure in 12-week-old C57BL/6 male mice." (PMID 28743963, 2017). "Together, these data demonstrate that AGGF1 overexpression by gene delivery via AAV9 viruses can successfully inhibit cardiac hypertrophy and improve cardiac function." (PMID 28743963, 2017). "Six weeks after TAC, Aggf1+/− mice showed more severe cardiac hypertrophy than WT mice by hematoxylin and eosine (H&E) staining." (PMID 28743963, 2017). "Our data suggest that AGGF1 regulates ER stress signaling pathways, and blocks ER stress-induced apoptosis, cardiac hypertrophy, and heat failure." (PMID 28743963, 2017). "In this study, we investigated the physiological role of Aggf1 in the heart using Aggf1+/− mice and unraveled a novel role of Aggf1 in regulating ER stress signaling, cardiac hypertrophy, and heart failure." (PMID 28743963, 2017). "We found that Aggf1 had an important pathophysiological role in the development of cardiac hypertrophy and heart failure." (PMID 28743963, 2017). "The present study has identified a novel in vivo physiological role of AGGF1 in regulating ER stress signaling, and blocking ER stress-induced apoptosis, cardiac hypertrophy, and heart failure." (PMID 28743963, 2017). "The cross-sectional diameter of cardiomyocytes and the plasma level of atrial natriuretic factor (ANF), a sensitive biomarker for cardiac hypertrophy and heart failure, were increased more in Aggf1+/− mice than in WT mice after TAC." (PMID 28743963, 2017). "On the other hand, AGGF1 protein therapy inhibits cardiac hypertrophy and heart failure by blocking ER stress-induced cardiomyocyte apoptosis." (PMID 28743963, 2017). "Our studies in mouse models have indicated that AGGF1 protein therapy is a novel treatment strategy for cardiac hypertrophy and heart failure." (PMID 28743963, 2017). "It is of high interest that AGGF1 protein therapy inhibited cardiac hypertrophy and heart failure and restored myocardial function (LVEF and LVFS) to nearly normal levels by blocking ER stress-induced apoptosis." (PMID 28743963, 2017). "The studies with the miR-183-5p inhibitor showed that AGGF1 acts upstream of miR-183-5p in regulating cardiac hypertrophy and heart failure." (PMID 28743963, 2017). "H&E staining showed that AGGF1 therapy reduced cardiac hypertrophy and heart failure in 6-week-old TAC mice, but the therapeutic effect was lost in the presence of the Antago-miR-183-5p inhibitor." (PMID 28743963, 2017). "AGGF1 overexpression inhibited cardiac hypertrophy, improved cardiac function, and reduced the ratios of HW/BW and LW/BW, and the cross-sectional diameter of cardiomyocytes." (PMID 28743963, 2017). "H&E staining showed that TAC induced cardiac hypertrophy, but AGGF1 protein therapy resulted in less enlargement of the hearts compared with phosphate-buffered saline (PBS) treatment." (PMID 28743963, 2017). "AGGF1 protein therapy and miR-183-5p regulate endoplasmic reticulum stress signaling and block endoplasmic reticulum stress-induced apoptosis, cardiac hypertrophy, and heart failure, providing an attractive paradigm for treatment of cardiac hypertrophy and heart failure." (PMID 28743963, 2017). "On the other hand, increased angiogenesis by the AGGF1 protein therapy may suppress cardiac hypertrophy and heart failure in TAC mice." (PMID 28743963, 2017).
cardiac hypertrophy (continued). "Here the authors uncover a pathway whereby AGGF1 blocks ER stress by inhibiting ERK1/2 activation and the transcriptional repressor ZEB1, leading to induction of miR-183-5p and down-regulation of CHOP, and show that AGGF1 can effectively treat cardiac hypertrophy and heart failure." (PMID 28743963, 2017). "To further identify the mechanism by which Aggf1 haploinsufficiency augments cardiac hypertrophy and heart failure, we analyzed CHOP and other ER stress signaling markers BiP, ERO1α, Puma, DR5, ATF4, cATF6, p-eIF2α, phosphorylated PERK (p-PERK), and sXBP1 using western blot analysis." (PMID 28743963, 2017). "The combined effect of AGGF1-induced autophagy and AGGF1-mediated ER stress signaling may be the key for the successful inhibition of cardiac hypertrophy and heart failure and increased myocardial function." (PMID 28743963, 2017). "Increased phosphorylation of eIF2α may be one of the major factors contributing to the suppression of cardiac hypertrophy by AGGF1 through the inhibition of protein synthesis." (PMID 28743963, 2017). "As AGGF1 abundance is reduced in patients and animal models with heart failure, we explored the potential of therapeutic treatment of cardiac hypertrophy and heart failure by targeted protein therapy via intravenous injection of recombinant AGGF1 (0.25 mg/kg BW)." (PMID 28743963, 2017). "AGGF1 protein therapy inhibited cardiac hypertrophy after MI." (PMID 27513923, 2016). "Therefore, it is possible that reduced angiogenesis and increased vascular permeability in Aggf1+/− mice may contribute to exacerbation of pathological cardiac hypertrophy in these mice." (PMID 28743963, 2017). "H&E staining and echocardiography showed that there is an additive effect for Aggf1 haploinsufficiency and TAC in inducing cardiac hypertrophy and heart failure, which was rescued by Ago-miR-183-5p." (PMID 28743963, 2017). "We induced cardiac hypertrophy and heart failure in Aggf1+/− mice using transverse aortic constriction (TAC), a well-established model for cardiac hypertrophy and heart failure in small animals." (PMID 28743963, 2017). "It is interesting to note that the Ago-miR-183-5p mimics and Antagomir-miR-183-5p inhibitor also have a major impact on cardiac hypertrophy and dysfunction upon pressure overload regardless of Aggf1 expression or AGGF1 protein treatment, respectively." (PMID 28743963, 2017). "We discovered a noncanonical signaling pathway, AGGF1-ERK-ZEB1-miR-183-5p-CHOP, that blocks ER stress-induced apoptosis and cardiac hypertrophy." (PMID 28743963, 2017).
glioma (2 papers, 2020). A benign or malignant brain and spinal cord tumor that arises from glial cells (astrocytes, oligodendrocytes, ependymal cells). "FOXP2 could also promote AGGF1 expression at the transcriptional level, thus enhancing proliferation and migration of vascular endothelial cells exposed to glioma." (PMID 32183046, 2020). "AGGF1 could promote angiogenesis in glioma-exposed endothelial cells, which was regulated by FOXP2 at the transcription level." (PMID 32183046, 2020). "Hence, circ-SHKBP1 modulated glioma angiogenesis through targeting miR-544a/FOXP1/AGGF1 and miR-379/FOXP2/AGGF1 pathway." (PMID 32061256, 2020).
Hyperglycemia (2 papers, 2020 to 2024). An increased concentration of glucose in the blood. "In diabetic mice, AGGF1 counteracts the damaging effect of hyperglycemia on endothelial progenitor cells." (PMID 38904047, 2024). "Through activating Akt and inhibiting reactive oxygen species generation, AGGF1 reduced the damaging effects of hyperglycemia on endothelial progenitor cells (EPCs) in vivo." (PMID 32183046, 2020). "Studies have found that AGGF1 could activate Akt and inhibit the production of reactive oxygen species, thus reversing all the destructive effects of hyperglycemia on endothelial progenitor cells." (PMID 32183046, 2020).
myocardial ischemia (2 papers, 2017 to 2018). A disorder of cardiac function caused by insufficient blood flow to the muscle tissue of the heart. "Aggf1 maintained vascular integrity by inhibiting VE-cadherin phosphorylation in myocardial ischemia/reperfusion models." (PMID 29885663, 2018). "Recent studies showed that Aggf1 possessed the protective roles by activating PI3K/Akt pathway in myocardial ischemia-reperfusion injury and in cell cultures." (PMID 29885663, 2018). "During myocardial ischemia-reperfusion injury, Aggf1 was proven to decrease the release of inflammatory molecules and decrease infarct size." (PMID 29885663, 2018). "Aggf1 was proved to reduce the release of inflammatory molecules in myocardial ischemia model." (PMID 29885663, 2018). "Enforced expression of AGGF1 could enhances angiogenesis and improve the blood supply, this may be a treatment or protection for ischemic hindlimbs and myocardial ischemia/reperfusion injury." (PMID 29340079, 2017).
aortic aneurysm (1 paper, 2023). A ruptured aneurysm located in the wall of the proximal portion of the descending aorta proceeding from the arch of the aorta. "To develop a pharmacologic therapy for aortic aneurysms, we examined the effects of AGGF1 protein therapy." (PMID 37081014, 2023). "Taken together, all these data indicate that AGGF1 protein therapy is effective in blocking the development of aortic aneurysms in the ascending aortas in the BAPN-induced mouse model." (PMID 37081014, 2023). "First, using TAC mice as a model for pressure-overload-induced vascular inflammation and remodeling associated with aortic aneurysms in both carotid arteries and ascending aortas in TAC mice, we showed that vascular remodeling significantly decreased the expression of AGGF1." (PMID 37081014, 2023). "To further study the reduced expression of AGGF1 by vascular remodeling as in TAA patients, we studied TAC mice, a pressure-overload model for aortic aneurysms." (PMID 37081014, 2023).
atherosclerosis (1 paper, 2021). A disease characterized by the build-up of fatty material and calcium deposition in the arterial wall resulting in partial or complete occlusion of the arterial lumen. "Of these genes, A2ML1, AGGF1, CBS, ECE1, GABRB3, GALNT2, MRPS6/SLC5A3, and SPG7 had documented associations with hypertension, ischemic stroke and methionine metabolism, atherosclerosis, and early-onset MI." (PMID 34252155, 2021).
cardiac arrest (1 paper, 2022). Cessation of breathing and/or cardiac function. "In Aggf1(-/-) group, 4 rats died of respiratory or cardiac arrest during blood injection process." (PMID 35259055, 2022).
Cirrhosis (1 paper, 2017). A chronic disorder of the liver in which liver tissue becomes scarred and is partially replaced by regenerative nodules and fibrotic tissue resulting in loss of liver function. "Interestingly, the other conventional clinicopathological parameters, such as gender (P=0.81), age (P=0.99), AFP (P=0.24), HBsAg (P=0.85), ALT (P=0.72), Cirrhosis (P=0.40), tumor size (P=0.65, all done by chi-square test), none of them was significantly correlated with AGGF1 expression." (PMID 29340079, 2017).
colorectal cancer (1 paper, 2019). A primary or metastatic malignant neoplasm that affects the colon or rectum. "However, the differential expression as well as the biological functions of AGGF1 in colorectal cancer (CRC) remain to be established." (PMID 31881864, 2019).